BAP1 (BRCA1 associated deubiquitinase 1)
Diseases named in the same sentence as BAP1 in open-access papers (continued):
Sharing a sentence is not in itself a finding about the gene and the disease.
cutaneous melanoma (continued). "Therefore, the finding that BAP1 promotes the repair of UV-damaged DNA in primary melanocytes may explain why cutaneous melanomas and skin cancers—often caused by UV radiation—are prevalent in carriers of germline BAP1 mutations." (PMID 37009801, 2023). "Germline BAP1 mutations are indeed associated with a cancer syndrome characterized by an increased risk of malignant mesothelioma, atypical melanocytic tumors (melanocytic BAP1-mutated atypical intradermal tumors), uveal and cutaneous melanoma, and other neoplasms." (PMID 33322357, 2020). "However, data on BAP1 mutational status in skin melanoma are still missing." (PMID 31780644, 2019). "UM tumors are frequently detected with mutations in GNA11, GNAQ, EIF1AX, BAP1, and SF3B1 instead of the typical mutations associated with cutaneous melanoma." (PMID 40283643, 2025). "Whilst there is a clear association of cutaneous melanoma and BIM with BAP1 GPV, the exact risk of cutaneous malignancy is unclear." (PMID 37607989, 2023). "Loss of expression of BAP1 due to germline variants in this gene has been associated with the development of BCC, uveal and cutaneous melanomas." (PMID 34284772, 2021). "Despite this, a recent meta-analysis based on TCGA dataset described opposite roles of BAP1 in survival of uveal and cutaneous melanoma." (PMID 33800394, 2021). "In contrast to its role as a tumor suppressor gene, BAP1 expression in cutaneous melanoma was found to promote growth and survival of cells." (PMID 32429485, 2020). "In cutaneous melanoma cell lines, however, stable over-expression of BAP1 promoted cell growth while knockdown of BAP1 suppressed cell proliferation with concomitant decrease of survivin, an anti-apoptotic protein." (PMID 32028647, 2020). "When CM is the only BAP1-TPDS-associated malignancy present in an individual or family, the threshold for familial CM should be ≥3 cutaneous melanomas in one individual or in the family, given its high frequency in the general population in the Netherlands." (PMID 31382694, 2019). "In summary, this finding expands on the growing profile of BAP1 as an important uveal and cutaneous melanoma suppressor gene." (PMID 23977234, 2013). "The finding expands on the growing profile of BAP1 as an important uveal and cutaneous melanoma tumor suppressor gene and implicates its involvement in the development of lung, and stomach cancer." (PMID 23977234, 2013). "Sequencing of exons 4–13 and 15–17 of BAP1 was performed on Study Subjects 3 (pedigree C) and 7 (pedigree G), both of whom had a personal history of uveal and cutaneous melanoma." (PMID 23825798, 2013). "Thus, while the findings of this trial are mildly encouraging for the use of Niraparib in BAP1 mutant patients, it is challenging to ascertain its specific utility for cutaneous melanoma." (PMID 40842586, 2025). "Cutaneous melanoma arising in patients with BAP1 germline mutation develop de‐novo without precursor in majority of patients." (PMID 39268598, 2025). "BAP1 immunohistochemistry also has an important role in the diagnosis and classification of malignant pleural mesothelioma, epithelioid atypical Spitz tumors, cutaneous melanoma, and clear cell renal cell carcinoma." (PMID 34771510, 2021). "The loss of BAP1 expression, although not frequent in cutaneous melanoma, was independently associated with poor DFS and MSS." (PMID 28404968, 2017). "Our work thus motivates further studies to elucidate the potential link between BAP1 and SLC7A11 in human skin melanoma." (PMID 31780644, 2019). "In line with earlier observations in skin melanoma cells, these effects were independent of the mutational status (GNAQ, GNA11, BAP1, BRAF and NRAS) of the UM and CM cell lines." (PMID 34508176, 2022). "However, BAP1 has been reported to deubiquitinate KLF5 and to promote breast cancer cell proliferation and metastasis and to play a pro-survival role in cutaneous melanoma." (PMID 30669483, 2019).
malignant mesothelioma (94 papers, 2012 to 2026). A malignant neoplasm of the pleura or peritoneum, arising from mesothelial cells. "Current pathology guidance also notes that BAP1 loss is typical of malignant mesothelioma but is retained in benign lesions—helpful when morphology is subtle." (PMID 41295231, 2025). "The loss of BAP1 is known as a highly specific marker for distinguishing malignant mesothelioma from reactive proliferation." (PMID 39896180, 2024). "Given these encouraging preclinical results, it will be important to clinically explore dual EZH2/FGFR inhibition in patients with BAP1-deficient malignant mesothelioma and justify further exploration in other BAP1 loss–associated tumors." (PMID 38054839, 2024). "Taken together, our in vitro results show a high synergistic potential for combining FGFR and EZH2 inhibition against BAP1-deficient malignant mesothelioma." (PMID 38054839, 2024). "A study by Hmeljak and colleagues showed that the overall prevalence of BAP1 alterations in malignant mesothelioma is 57%, of which 96% were inactivating mutations." (PMID 38519707, 2024). "The association of BAP1 loss with chromosome instability is clearly found in malignant mesothelioma." (PMID 37009801, 2023). "BRCA1-associated protein 1 (BAP1) mutations are found in several aggressive cancers, including malignant mesothelioma." (PMID 37445594, 2023). "BRCA1‐associated protein 1 (BAP1) is a tumor suppressor gene and its loss has been reported in malignant mesothelioma." (PMID 36873079, 2023). "Wilms tumor 1 (WT1)/AE1/AE3, claudin 4, and BRCA1‐associated protein 1 (BAP1) immunostains are useful new tools that have been proposed for the distinction between Malignant Mesothelioma and benign mesothelial reactions." (PMID 36069384, 2022). "Here, we describe a case of familial malignant mesothelioma in a 39 years old patient with a confirmed BAP1 mutation in addition to a known family history with the same mutation." (PMID 35360426, 2022). "There was a statistically significant association between BAP1 and EZH2 expression (p = 0.008), where 67.3% of cases of BAP1 loss showed low EZH2 and 62.5% of malignant mesothelioma cases with retained BAP1 showed high EZH2 expression." (PMID 34257556, 2021). "Apart from the environmental exposure, the development of malignant mesothelioma has been linked to a mutation in the BAP1 gene, which can predispose the patient to develop other malignancies associated with BAP1 mutation." (PMID 34725624, 2021). "BAP1 loss is caused by mutations, deletions or epigenetic silencing of BAP1 in both familial and sporadic malignant mesothelioma." (PMID 34257556, 2021). "BRCA1-associated protein 1 (BAP1) is a newly identified diagnostic marker whose loss is specific to malignant mesothelioma." (PMID 34257556, 2021). "Genome-wide sequencing analyses of malignant mesotheliomas have revealed frequently observed genomic aberrations such as loss of function mutation and/or copy number alterations/deletion of BAP1, SETD2, CDKN2A, and NF2." (PMID 32545767, 2020). "Recent works demonstrated how BRCA1-associated protein-1 (BAP1) is expressed in nearly one-third of malignant mesotheliomas." (PMID 33419364, 2020). "These mutations have been associated with various malignancies other than malignant mesothelioma such as, uveal melanoma and melanocytic BAP1-associated intradermal tumors." (PMID 29666782, 2018). "In cases of malignant mesothelioma that have been linked to environmental exposure, BAP1 mutations have mainly been seen in younger population with equal gender and pleural/peritoneal distribution." (PMID 30410729, 2018). "Since we found that BAP1 activity is tightly regulated by UBE2Es-mediated ASXL2 monoubiquitination, we analyzed protein expression of these proteins in malignant mesothelioma, a cancer characterized by a high frequency of BAP1 mutations." (PMID 30349006, 2018).
malignant mesothelioma (continued). "Lack of nBAP1 protein expression is associated with loss of function mutations of BAP1 and is common in several human cancers such as uveal and oral mucosal melanoma and malignant mesothelioma." (PMID 30060843, 2018). "BAP1 is the only gene reported to be in a causal pathway for malignant mesothelioma development in connection with asbestos exposure." (PMID 30410729, 2018). "The discovery of the role of BAP1 mutations in malignant mesothelioma is an example of the combination between classical genetic methods and novel high-throughput technologies to discover causal relationships between genotype and phenotype." (PMID 30060501, 2018). "BAP1 germ line mutation has been found to be a risk factor for the development of malignant mesothelioma in families where the mutation is found in 50% of members." (PMID 30410729, 2018). "Loss of BAP1 is responsible for the process of malignant mesothelioma, and the homozygous deletion of BAP1 are associated with loss of IHC staining, thus leading to the high specificity of BAP1 in IHC." (PMID 28978163, 2017). "Germline BAP1 mutations have been recently associated with an increased risk of malignant mesothelioma, atypical melanocytic tumors and other neoplasms." (PMID 22935333, 2012). "We recently identified two unrelated families (L and W) with germline BAP1 mutations and increased risk of malignant mesothelioma (MM) and possibly other cancers." (PMID 22935333, 2012). "Moreover, approximately 22% of all BAP1 germline mutations carriers will develop a malignant mesothelioma during their life." (PMID 38673021, 2024). "Asbestos and BAP1 germline mutations are risk factors for malignant mesothelioma (MM)." (PMID 38592450, 2024). "Furthermore, patients with malignant mesothelioma and germline BAP1 mutations exhibited 7 times longer long-term survival compared to patients without germline BAP1 mutations." (PMID 39267830, 2024). "In addition, mice carrying heterozygous germline BAP1 mutations developed various spontaneous tumors and were predisposed to the development of malignant mesothelioma after exposure to asbestos carcinogenic fibers." (PMID 37009801, 2023). "In addition to mutations of BAP1, frequent deletion of tumour suppressors Cdkn2a/b and Nf2 were observed in malignant mesothelioma." (PMID 36318367, 2022). "BAP1 is a newly identified diagnostic marker whose loss is specific to malignant mesothelioma." (PMID 34257556, 2021). "Case studies have reported WDPMs with somatic mutation of E2F1, heterozygous loss of NF2, and germline BAP1 mutation, which if correct would suggest that they may be variants of malignant mesothelioma." (PMID 32545767, 2020). "Interestingly, it has been shown that germline mutations in Bap1 can induce epigenetic deregulation of the Rb protein in mice, facilitating the development of malignant mesothelioma." (PMID 30060501, 2018). "In addition, SV40 in contaminated polio vaccines, and germline BAP1 mutations have been associated with malignant mesothelioma." (PMID 28817672, 2017). "However, because the researchers compared the asbestos exposure histories provided by the participants with historical records, we can consider another possibility, which is that a genetic mutation in the BAP1 tumor suppressor gene predisposes individuals to malignant mesothelioma and lung cancer." (PMID 36498008, 2022). "Loss of BAP1 and MTAP expression was instrumental in distinguishing malignant mesothelioma from benign mesothelial proliferations in this patient." (PMID 40662041, 2025). "To increase the clinical relevance and to validate the findings from our mouse cell lines, we performed a similar screen in 8 human malignant mesothelioma cell lines (4 BAP1 mutant, 4 BAP1 wild-type)." (PMID 38519707, 2024). "BMPM immunohistochemistry is also positive for BAP-1, specifically expressed in adenomatoid tumors, and D2-40, a highly sensitive marker for malignant mesothelioma." (PMID 38899248, 2024).
malignant mesothelioma (continued). "More than half of patients with malignant mesothelioma show alterations in the BAP1 tumor-suppressor gene." (PMID 36657447, 2023). "Combined mutations of BAP1, NF2, and CDKN2A are observed in about 34% of malignant mesothelioma, indicating the importance of these tumor suppressors in the disease pathogenesis." (PMID 35204459, 2022). "Mice lacking Bap1 also exhibit myeloid transformation and spontaneous malignant mesothelioma, demonstrating that BAP1 is a bona fide tumor suppressor." (PMID 35052618, 2022). "After confirmation of the mesothelial lineage, BAP1 loss, CDKN2A homozygous deletion, and MTAP loss were the most specific markers for the diagnosis of malignant mesothelioma." (PMID 35205689, 2022). "IHC staining for BAP1 is lost in a substantial subset of malignant mesotheliomas but retained in benign mesothelial proliferations." (PMID 36069384, 2022). "In malignant mesothelioma, it was demonstrated that EZH2 mRNA expression was elevated, yet EZH2 IHC expression and its association with BAP1 in malignant mesothelioma have not been fully understood." (PMID 34257556, 2021). "EZH2 overexpression is reported in different cancers, but its relation to BAP1 in malignant mesothelioma has not been fully understood." (PMID 34257556, 2021). "BAP1 is a relatively new marker for the diagnosis of malignant mesothelioma and its utility has been demonstrated in several studies." (PMID 34257556, 2021). "We have generated mouse models of malignant mesothelioma (MM) based upon disruption of the Bap1, Nf2, and Cdkn2ab tumor suppressor loci in various combinations as also frequently observed in human MM." (PMID 32271879, 2020). "The loss of BAP1 and CDKN2A are genetic events shown to effectively differentiate between malignant mesothelioma and reactive mesothelial hyperplasia." (PMID 30060501, 2018). "Since SV40 and BAP1 tests are uncommon in South Korea, the possibility of malignant mesothelioma due to these factors cannot be excluded." (PMID 28817672, 2017). "Further studies are needed regarding the potential associations between malignant mesothelioma and SV40 exposure and BAP1 mutations." (PMID 28817672, 2017). "Although neither BAP1 nor CDKN2A mutations provide absolute specificity in diagnosing malignant mesothelioma, they remain invaluable adjuncts for differentiating PM from benign pleural lesions and prognostic assessment." (PMID 40904706, 2025). "Thus, our Bap1 mouse models, which closely mimic human malignant mesothelioma, provide an ideal genetic setting for identifying synthetic lethal interactions and investigating the BAP1-polycomb connections in cancer." (PMID 36657447, 2023). "Therefore, integrating different methodologies is advisable to evaluate all nuances of BAP1 gene alterations in malignant mesotheliomas." (PMID 36765620, 2023). "The finding of the loss of BAP1 is 100% specific for malignant mesothelioma, and it has not been reported in benign mesothelial proliferation." (PMID 35950141, 2022). "In the patient with a confirmed PR, the tumor did not harbor a PIK3CA mutation or PTEN loss but an alteration in the BAP1 gene (exon 3 p.D34fs), a potent tumor suppressor implicated in PI3K signaling pathway and in the pathogenesis of malignant mesothelioma, was found." (PMID 33660194, 2021). "Additionally, a decrease in the level of BRCA1 protein has been observed in the malignant mesothelioma cells with BAP1 deletion, while transduction of the mutants as well as WT BAP1 results in an increase in the level of BRCA1 protein." (PMID 30716094, 2019). "Histopathologic examination confirmed malignant mesothelioma of epithelioid type, supported by immunohistochemical reactivity for calretinin, cytokeratin 7 (CK7), cytokeratin 5/6 (CK5/6), pan-cytokeratin (PanCK), Wilms tumor 1 (WT1), and loss of BRCA1-associated protein-1 (BAP1)." (PMID 40978995, 2025).
malignant mesothelioma (continued). "BAP1 is retained in almost all serous carcinomas, making it useful to differentiate between malignant mesothelioma and serous carcinoma, additional panel could include paired box 8 (PAX8) (usually positive in serous carcinoma) and calretinin (usually positive in mesothelial cells)." (PMID 36069384, 2022). "Rare germline mutations in BAP1 contribute to predispositions in malignant mesothelioma, among other cancers, despite lack of exposure to high levels of asbestos or other carcinogens, suggesting that BAP1 may serve as a predictive biomarker." (PMID 29342862, 2018). "Malignant mesothelioma or other BAP1 associated cancers occurring at a young age, i.e., 50 years old or younger, or occurring in multiple family members—regardless of age—should trigger testing for germline BAP1 mutations." (PMID 30001711, 2018). "We next investigated the influence of the protein expression of BAP1, NF2, CDKN2A, and LAG3 on the malignant mesothelioma TIME." (PMID 38994676, 2024). "The primary objective of this study was to advance our understanding of the malignant mesothelioma TIME while examining the protein expression levels for LAG3, BAP1, NF2, and methylthioadenosine phosphorylase (MTAP)." (PMID 38994676, 2024). "Immunohistochemical detection of BAP1 and EZH2 is a reliable marker for differentiating benign mesothelial proliferation from malignant mesothelioma." (PMID 37461124, 2023). "The deletion of BAP1 and high expression of EZH2 were both observed in malignant mesothelioma, which were merely observed in benign lesions." (PMID 36195655, 2022). "Despite these limitations, this meta-analysis suggested BAP1 IHC as a promising marker with extremely high specificity, and good DOR and area under curve in diagnosing malignant mesothelioma." (PMID 28978163, 2017). "In addition to the immune checkpoint LAG3, BAP1, NF2, and MTAP were chosen as proxies to represent commonly altered TSG products in malignant mesothelioma." (PMID 38994676, 2024). "BAP1 and CDKN2A gene mutations do not have a 100% specificity for the diagnosis of malignant mesothelioma, but they can help distinguish MPM from benign pleural diseases." (PMID 37461124, 2023). "Indeed, our most important finding is the lack of alterations involving BAP1, SETD2, NF2, CDKN2A, PBRM1, and SMARCC1 genes consistently mutated or deleted in malignant mesotheliomas." (PMID 32545767, 2020). "The WDPMs lacked the alterations involving BAP1, SETD2, NF2, CDKN2A/B, LASTS1/2, PBRM1, and SMARCC1 that are frequently found in malignant mesotheliomas." (PMID 32545767, 2020).